FMR1 (fragile X messenger ribonucleoprotein 1)
Diseases named in the same sentence as FMR1 in open-access papers (continued):
Sharing a sentence is not in itself a finding about the gene and the disease.
fragile X-associated tremor/ataxia syndrome (continued). "Fragile X associated tremor/ataxia syndrome (FXTAS) is a neurodegenerative disease caused by aberrant expansion of CGG repeats in 5′ UTR of FMR1 gene." (PMID 23626835, 2013). "The fragile X-associated tremor/ataxia syndrome (FXTAS) is a late-onset neurodegenerative disorder caused by expansions of 55-200 CGG repeats in the 5'UTR of the FMR1 gene." (PMID 21639881, 2011). "Fragile X-associated tremor/ataxia syndrome (FXTAS) is caused by the premutation (55–200 CGG repeats) of the fragile X mental retardation 1 (FMR1) gene." (PMID 23008705, 2011). "More recent studies reveal that premutation alleles of the FMR1 gene are associated with several medical conditions, and the two most studied topics are Fragile X-associated tremor/ataxia syndrome (FXTAS) and Fragile X-associated primary ovarian insufficiency (FXPOI)." (PMID 37200782, 2023). "The FMR1 premutation has been linked to other disorders such as a late-onset neurodegenerative syndrome, fragile X-associated tremor/ataxia syndrome (FXTAS), fragile X-associated neuropsychiatric disorder (FXAND), and fragile X-associated primary ovarian insufficiency (FXPOI)." (PMID 36861076, 2023). "Fragile X syndrome (FXS), and its related diseases-fragile X-associated immature ovarian insufficiency (FXPOI) and fragile X-associated tremor/ataxia syndrome (FXTAS)-are caused by the expansion of a CGG repeat tract located in the 5′-UTR of fragile X mental retardation 1 gene (FMR1)." (PMID 35203324, 2022). "Fragile X-associated tremor/ataxia syndrome (FXTAS) is one of these repeat expansion disorders characterized by a CGG or GGC repeat expansion (55–200 repeats) in the 5′ UTR of the Fragile X Mental Retardation 1 (FMR1) gene." (PMID 34054431, 2021). "Fragile X-associated tremor/ataxia syndrome (FXTAS) is a late-onset neurodegenerative monogenetic disorder affecting carriers of premutation (PM) forms of the FMR1 gene, resulting in a progressive development of tremors, ataxia, and neuropsychological problems." (PMID 32219099, 2020). "Premutation carriers do not show early-childhood-onset intellectual disability syndrome, and paradoxically, they have abnormally high levels of FMR1 mRNA, which predisposes them to a late-onset neurodegenerative disorder called fragile X-associated tremor/ataxia syndrome (FXTAS)." (PMID 31991700, 2020). "In individuals carrying premutation alleles the FMR1 mRNA levels are increased and progressively accumulates in inclusions that result in the fragile X-associated Tremor Ataxia syndrome (FXTAS) (MIM# 300623), a late onset autonomic disorder with cognitive dysfunction." (PMID 30450110, 2018). "Additionally, a CGG repeat in the 5′ UTR of the neurodegenerative disease fragile X-associated tremor/ataxia syndrome (FXTAS)-linked FMR1 also gives rise to RAN translation products." (PMID 25806046, 2015). "The fragile X-associated tremor/ataxia syndrome (FXTAS) is a neurodegenerative disorder caused by the premutation (55–200 CGG repeats) in the fragile X messenger ribonucleoprotein-1 (FMR1) gene." (PMID 41509710, 2026). "Fragile X-associated tremor/ataxia syndrome (FXTAS) is a late-onset neurodegenerative disorder caused by moderately expanded CGG trinucleotide repeats in the 5′ untranslated region (UTR) of the FMR1 gene." (PMID 40003975, 2025). "Fragile X-associated tremor/ataxia syndrome (FXTAS) is a neurodegenerative disorder impacting a subset of individuals with the premutation allele of the Fragile X Messenger Ribonucleoprotein 1 (FMR1) gene located on the X chromosome." (PMID 41300783, 2025). "Individuals with the FMR1 premutation are at risk of developing fragile X-associated tremor/ataxia syndrome (FXTAS), a late-onset neurodegenerative disorder." (PMID 40362640, 2025).
fragile X-associated tremor/ataxia syndrome (continued). "In the last few years, researchers reported the association between neurological symptoms and the IAs in the genes responsible for SCAs and the IAs in the FMR1 gene responsible for fragile X-associated tremor/ataxia syndrome (FXTAS)." (PMID 37906407, 2024). "Fragile X-associated tremor/ataxia syndrome (FXTAS) is a neurodegenerative disorder caused by CGG repeat expansion of FMR1 gene." (PMID 38714961, 2024). "Fragile X-associated tremor/ataxia syndrome (FXTAS) is a late-onset neurodegenerative disorder affecting premutation carriers of the FMR1 gene." (PMID 39445272, 2024). "Fragile X-associated tremor/ataxia syndrome (FXTAS) is a late-onset neurodegenerative disorder that appears in adult FMR1 premutation carriers." (PMID 37830578, 2023). "This mRNA is associated with the common genetic disease FXTAS (Fragile X-associated tremor/ataxia syndrome) that arises from an increased number of CGG repeats (55–200 copies) in the 5′-UTR of the fmr1 gene." (PMID 37391423, 2023). "Along the same line, it has been shown that about 39% of the male carriers of the expanded CGG repeats of the fragile X mental retardation gene (FMR1) present fragile X-associated tremor/ataxia syndrome (FXTAS)." (PMID 37296608, 2023). "Fragile X-Associated Tremor/Ataxia Syndrome (FXTAS) is one of the most severe late-onset movement disorders caused by a specific change in the major Fragile X Messenger Ribonucleotide 1 (FMR1) gene." (PMID 36421873, 2022). "Fragile X-associated tremor/ataxia syndrome (FXTAS) is a neurodegenerative condition accompanying a permutation repeat expansion (55–200 CGG repeats) in the 5′ noncoding region of the FMR1 gene." (PMID 35093121, 2022). "As an example, Fragile X-associated tremor/ataxia syndrome (FXTAS) is caused by the expansion of CGG repeats in the pre-mutation rate (55–200 repeats) within the 5′ UTR of the FMR1 gene." (PMID 36142405, 2022). "FMR1 premutation is causally linked to fragile X-associated tremor/ataxia syndrome (FXTAS) and is the most prevalent monogenic NDD risk factor." (PMID 34924936, 2021). "We also tested the C9ORF72 antisense CCCCGGexp and FMR1 CGGexp in fragile X-associated tremor/ataxia syndrome (FXTAS)." (PMID 34389711, 2021). "Fragile X-associated tremor/ataxia syndrome (FXTAS) is an incurable neurodegenerative disorder caused by expansion of CGG repeats in the FMR1 5’UTR." (PMID 33627639, 2021). "Fragile X-associated Tremor/Ataxia Syndrome (FXTAS) is a late-onset neurodegenerative disorder, mostly affecting carriers of the fragile X mental retardation 1 (FMR1) gene mutation after the age of 50." (PMID 34483988, 2021). "Fragile X-associated tremor/ataxia syndrome (FXTAS) is a rare neurodegenerative disorder caused by a 55–200 CGG repeat expansion in the 5′ untranslated region of the Fragile X Mental Retardation 1 (FMR1) gene." (PMID 33381520, 2020). "FMR1 gene premutation carriers are at risk of developing Fragile X-associated tremor/ataxia syndrome (FXTAS) and Fragile X-associated primary ovarian insufficiency (FXPOI) in adulthood." (PMID 33195417, 2020). "The FMR1 premutation carriers are at risk of developing Fragile X-associated tremor/ataxia syndrome (FXTAS) and Fragile X-associated primary ovarian insufficiency (FXPOI) in adulthood, as well as other unspecific syndromes." (PMID 33195417, 2020). "Fragile X-associated Tremor/Ataxia Syndrome (FXTAS) is a neurodegenerative disease caused by a trinucleotide CGG repeat expansion in the 5′ untranslated region (UTR) of the FMR1 gene." (PMID 31665086, 2019). "Individuals with premutation alleles of the fragile X mental retardation 1 (FMR1) gene are at risk of developing fragile X-associated tremor/ataxia syndrome (FXTAS) during aging." (PMID 30665341, 2019). "Fragile X-associated tremor/ataxia syndrome (FXTAS) is a neurodegenerative disorder caused by a CGG-repeat expansion in the 5′ UTR of the FMR1 gene on the X-chromosome." (PMID 30984240, 2019).
fragile X-associated tremor/ataxia syndrome (continued). "Fragile X-associated tremor/ataxia syndrome (FXTAS) is a severe neurodegenerative movement disorder affecting over 40% of male and 16% of female FMR1 premutation carriers over the age of 50." (PMID 29988561, 2018). "Fragile X-associated tremor/ataxia syndrome (FXTAS) is a movement disorder caused by expansion in the trinucleotide CGG repeat in the promoter region in the fragile X mental retardation 1 (FMR1) gene." (PMID 29887875, 2018). "Fragile X-associated tremor/ataxia syndrome (FXTAS) is a neurodegenerative disorder caused by a premutation CGG repeat expansion (55–200 repeats) within the 5′ UTR of the fragile X gene (FMR1)." (PMID 28529475, 2017). "We analysed the CGG repeat length of the FMR1 gene of cases, with written consent, to exclude fragile X-associated tremor/ataxia syndrome (FXTAS)." (PMID 27797808, 2016). "For example, in mice with fragile X-associated tremor/ataxia syndrome (FXTAS), the fragile X mental retardation (FMR1) transcript is targeted by miR-221, miR-101, and miR-129-5p." (PMID 27867363, 2016). "Carriers of the fragile X premutation allele (fXPCs) have an expanded CGG trinucleotide repeat size within the FMR1 gene and are at increased risk of developing fragile x-associated tremor/ataxia syndrome (FXTAS)." (PMID 25698960, 2015). "Fragile X-associated tremor/ataxia syndrome (FXTAS) is an age-related neurodegenerative disorder caused by expanded CGG repeats in the 5′ untranslated region of the FMR1 gene." (PMID 25452762, 2014). "Over-expression of the CGG containing FMR1 transcript itself is linked to both an independent neurodegenerative disease, Fragile X-associated tremor/ataxia syndrome (FXTAS) and to premature ovarian failure." (PMID 19888420, 2009). "Fragile X-associated tremor/ataxia syndrome (FXTAS), caused by the FMR1 premutation allele, is associated with brain degeneration, yet the mechanisms behind this neurodegeneration still need to be elucidated." (PMID 41638369, 2026). "FMR1 premutation carriers (55–200 CGG repeats) are at risk for developing fragile X-associated tremor/ataxia syndrome (FXTAS), a late-onset neurodegenerative disorder, and the salient central nervous system (CNS) diagnostic feature is white matter hyperintensity in the MCP in males." (PMID 40362640, 2025). "Among the 4 subjects with FMR1 diseases findings, there were 3 full mutations (FRAXA), and 1 premutation (fragile X-associated tremor/ataxia syndrome (FXTAS)." (PMID 38587680, 2024). "Fragile X-Associated Tremor/Ataxia Syndrome (FXTAS), typically caused by a premutation in the FMR1 (fragile X messenger ribonucleoprotein 1) gene, is a nervous system disorder in older adults characterized by tremors, ataxia, memory issues, and mood disorders." (PMID 39421616, 2024). "The presence of 55–200 repeats is considered an FMR1 premutation, which is associated with fragile X-associated tremor/ataxia syndrome (FXTAS, MIM 300623) and, in female individuals, with fragile X-associated premature ovarian insufficiency (FXPOI; MIM 311360)." (PMID 37420260, 2023). "The combination of ataxia and tremor is also the clinical hallmark of fragile X-associated tremor/ataxia syndrome (FXTAS), a late-onset neurodegenerative disorder affecting predominantly males carrying a premutation allele in the FMR1 gene on chromosome X." (PMID 37814130, 2023). "Additionally, about 15% of women with the FMR1 premutation will develop a late-onset neurodegenerative disease, fragile X-associated tremor/ataxia syndrome (FXTAS), characterized by ataxia, tremor, cognitive decline, and dementia." (PMID 35026985, 2022). "Fragile X-associated tremor/ataxia syndrome (FXTAS, OMIM# 300623) is a late-onset neurodegenerative disorder with reduced penetrance that appears in adult FMR1 premutation carriers (55–200 CGGs)." (PMID 36688175, 2022).
fragile X-associated tremor/ataxia syndrome (continued). "Fragile X-associated tremor/ataxia syndrome (FXTAS), caused by a trinucleotide CGG expansion in the FMR1 gene, is found in 2 to 4% of men with adult-onset CA and a negative family history." (PMID 34224032, 2021). "Fragile X-associated tremor/ataxia syndrome (FXTAS), which is caused by a CGG repeat expansion in the 5ʹ-UTR region of FMR1, and NIID display striking similarities in clinical features and histological findings of intranuclear inclusions." (PMID 34774111, 2021). "FMR1 was severely up-regulated in premutated individuals who might develop the fragile X-associated tremor/ataxia syndrome (FXTAS)." (PMID 32824515, 2020). "Shorter (60 < n < 200) repeat expansions cause the neurodegenerative Fragile X-associated tremor/ataxia syndrome (FXTAS), in which increased repeat-containing FMR1 transcripts are believed to cause a toxic RNA GOF." (PMID 32876811, 2020). "Fragile X-associated tremor/ataxia syndrome (FXTAS) is a progressive X-linked neurodegenerative disorder that arises from premutation CGG-repeat expansions (55-200 repeats) in the 5′ noncoding portion of the FMR1 gene." (PMID 31481131, 2019). "Individual carriers of a premutation allele in the FMR1 gene (55–200 CGG repeats) are at risk of developing Fragile X-associated tremor/ataxia syndrome (FXTAS) a late onset neurodegenerative disorder characterized by intentional tremor, gait ataxia, autonomic dysfunction, and Parkinsonism." (PMID 30186307, 2018). "Fragile X tremor ataxia syndrome (FXTAS) is a late-onset disorder manifesting in a proportion of FMR1 premutation individuals (PM: 55-199 CGG triplet expansions)." (PMID 27387142, 2016). "Fragile X-associated tremor/ataxia syndrome (FXTAS) and fragile X-associated primary ovarian insufficiency (FXPOI) are definitely related to the fragile X mental retardation 1 (FMR1) premutation (PM)." (PMID 27775646, 2016). "Fragile X-associated tremor/ataxia syndrome (FXTAS) is a neurodegenerative disorder that affects older adults who have a large CGG-repeat tract in the 5′-untranslated region (UTR) of the Fragile X Mental Retardation 1 (FMR1) gene." (PMID 25161746, 2014). "FXS is a family of disorders also including the FMR1 premutation disorders fragile X-associated primary ovarian insufficiency (FXPOI) and fragile X-associated tremor/ataxia syndrome (FXTAS)." (PMID 25232349, 2014). "The diagnosis of FXS in his granddaughter led to the re-assessment of his medical records and he was diagnosed retrospectively with fragile X-associated tremor/ataxia syndrome (FXTAS), which affects carriers, principally men, of premutation alleles of the FMR1 gene." (PMID 22738402, 2012). "The FMR1 gene is also the first single-gene cause of premature ovarian failure (fragile-X-associated premature ovarian insufficiency (FXPOI)) and one of the most common causes of ataxia (fragile-X-associated tremor/ataxia syndrome (FXTAS))." (PMID 39202368, 2024). "Fragile X-associated tremor/ataxia syndrome is a late-onset neurodegenerative disorder with reduced penetrance, meaning that not all FMR1 premutation carriers will develop it." (PMID 36688175, 2022). "Carrying the FMR1 premutation CGG repeat expansion (55–200 repeats) leads to two different phenotypes: fragile X-associated primary ovarian insufficiency (FXPOI) in females and fragile X-associated tremor/ataxia syndrome (FXTAS) mainly in males." (PMID 34238973, 2021). "Fragile-X tremor and ataxia syndrome (FXTAS), a Fragile-X mental retardation (FMR1) gene-related-phenotype, results from a pre-mutation condition with 55–200 200 CGG trinucleotide repeats and is characterized by paradoxically increased mRNA expression of FMR1." (PMID 34444449, 2021). "FXS and related syndromes, Fragile X Tremor Ataxia Syndrome (FXTAS) and Fragile X Premature Ovarian Failure (FXPOF), are X-linked disorders caused by expansion of a CGG triplet in the 5′ untranslated region (the promoter) of the FMR1 gene on the X chromosome." (PMID 32733828, 2020).
fragile X-associated tremor/ataxia syndrome (continued). "Fragile X associated tremor/ataxia syndrome (FXTAS) is a late adult-onset neurodegenerative disorder that affects movement and cognition in male and female carriers of a premutation allele of 55–200 CGG repeats in the Fragile X mental retardation (FMR1) gene." (PMID 32632326, 2020). "Premutations of the FMR1 gene involving 55–200 CGG repeats also confer risk for multiple subclinical issues as well as medical, psychiatric, and neurodegenerative conditions including fragile X-associated tremor/ataxia syndrome (FXTAS)." (PMID 31632248, 2019). "Fragile X Associated Tremor/Ataxia Syndrome (FXTAS) is a neurodegenerative movement disorder characterized by tremor, ataxic gait, and balance issues resulting from a premutation of the Fragile X Mental Retardation 1 (FMR1) gene." (PMID 31299981, 2019). "While the NS, GZ and PM alleles have an unmethylated FMR1 promoter and express FMRP, the PM alleles have been associated with adult onset disorders including fragile X-associated primary ovarian insufficiency (FXPOI) and the fragile X-associated tremor/ataxia syndrome (FXTAS)." (PMID 30959842, 2019). "Fragile X-associated tremor/ataxia syndrome (FXTAS) is a severe neurodegenerative movement disorder caused by premutation expansions (55–200 CGG repeats) in the 5′ untranslated region of the fragile X mental retardation 1 (FMR1) gene, located on the X-chromosome." (PMID 29988561, 2018). "As discussed in more detail below, many researchers have postulated that FMR1 mRNA gain-of-function toxicity may underlie FXPOI, as is the case for the other PM-associated disorder, fragile X-associated tremor/ataxia syndrome (FXTAS)." (PMID 25147583, 2014). "Individuals with 55–200 repeats are premutation carriers and generally express higher levels of FMR1 mRNA than normal individuals and may result in a clinical condition termed fragile X tremor and ataxia syndrome (FXTAS)." (PMID 18213394, 2008). "Among the X-linked ataxias, fragile X-associated tremor/ataxia syndrome (FXTAS), caused by a CGG repeat expansion in the premutation range in the 5′ non-coding region of the fragile X messenger ribonucleoprotein 1 (FMR1) gene is the most common." (PMID 38391932, 2024). "Fragile X-associated tremor/ataxia syndrome (FXTAS, OMIM# 300623) is a late-onset neurodegenerative disorder that appears in adult FMR1 (Fragile X Messenger Ribonucleoprotein 1) premutation carriers (55–200 CGGs)." (PMID 37830578, 2023). "Fragile X-associated tremor/ataxia syndrome (FXTAS) is one of these disorders, due to the expansion of the CGG repeat element at a noncoding region of the fragile X messenger ribonucleoprotein 1 (FMR1) gene in the premutation range (55–200 repeats)." (PMID 37508562, 2023). "Fragile X-associated tremor/ataxia syndrome (FXTAS) is a late adult-onset neurodegenerative disorder that affects movement and cognition in male and female carriers of a premutation allele (55–200 CGG repeats; PM) in the fragile X mental retardation (FMR1) gene." (PMID 34483988, 2021). "The premutation causes increased FMR1 mRNA levels that associates with slightly reduced FMRP expression and does not result in any neurodevelopmental syndrome, but can lead to the onset of Fragile X-associated Tremor/Ataxia Syndrome (FXTAS) after the age of 50 years." (PMID 34089433, 2021). "One of these repeat expansion-associated diseases, fragile X-associated tremor/ataxia syndrome (FXTAS), is caused by a CGG repeat expansion in the 5’UTR region of the fragile X mental retardation 1 (FMR1) gene." (PMID 34054431, 2021). "Premutations causing FMR1 mRNA overexpression and reduced FMRP synthesis, underly both fragile X-associated tremor/ataxia syndrome (FXTAS, OMIM #300623) and fragile X-associated primary ovarian insufficiency (FXPOI, OMIM #311360)." (PMID 33281866, 2020).